HK2 (hexokinase 2)
Diseases named in the same sentence as HK2 in open-access papers (continued):
Sharing a sentence is not in itself a finding about the gene and the disease.
placental disorders (1 paper, 2018). "For instance, we found hyperacetylation of regions near HK2, FLT1, and LEP, previously reported to be upregulated in other placental disorders, and hypoacetylation of regions near CH2 and CDLN1, which are involved in growth and endothelial cell-to-cell adhesions." (PMID 29983832, 2018).
Pleural effusion (1 paper, 2022). The presence of an excessive amount of fluid in the pleural cavity. "In our previous studies, we developed a hexokinase 2 (HK2)-based test for detecting rare tumor cells in multiple body fluids (e.g., pleural effusion, urine, blood, and cerebrospinal fluid) and cancers." (PMID 36172793, 2022).
polycystic kidneys (1 paper, 2018). "Compared with wild-type mice, Pkd1 miR Tg mice had significantly higher levels of Slc16a3 and Hk2 mRNA expression, indicating an increase in glycolytic activities in polycystic kidneys." (PMID 30585217, 2018).
polycystic ovary syndrome (1 paper, 2025). A disorder that manifests as multiple cysts on the ovaries. "The genes in question include several that play pivotal roles in metabolic processes, notably the HK2 gene, which exhibits reduced expression levels and a shortened polyadenylation tail in individuals with polycystic ovary syndrome." (PMID 40458121, 2025).
psoriasis (1 paper, 2023). An autoimmune condition characterized by red, well-delineated plaques with silvery scales that are usually on the extensor surfaces and scalp. "RT‒qPCR results showed that KCs from psoriasis patients expressed higher mRNA levels of glycolytic transporters (GLUT1) and glycolytic enzymes (PFKM, LDHA, HK2, PKM2, ENO1 and PGK1) than those from healthy skin." (PMID 37497003, 2023). "Consistently, RT‒qPCR results showed that K17 KO also downregulated the mRNA levels of the proliferation markers K17, K16, PCNA, Cyclin D1 and key enzymes (GLUT1, PFKM, LDHA, HK2, PKM2, ENO1 and PGK1) in the IMQ-induced psoriasis-like model." (PMID 37497003, 2023). "Moreover, Ki67 expression and the mRNA levels of proliferation markers K17, K16, PCNA, Cyclin D1 and key enzymes (GLUT1, PFKM, LDHA, HK2, PKM2, ENO1 and PGK1) were also decreased in epidermal KCs of the IMQ-induced psoriasis-like model with local application of BI-D1870." (PMID 37497003, 2023).
retinal disease (1 paper, 2023). "Previous work looking at single knockout of either HK2 or PKM2 in PRs suggests that altering expression or function of metabolic enzymes may be useful for preserving PRs during the metabolic stress experienced in retinal disease." (PMID 37626853, 2023).
Salmonella Infections (1 paper, 2022). Infections with bacteria of the genus SALMONELLA. "Meanwhile, mRNA and protein expressions of hexokinase-2 (HK2) and glucose transporters 4 (GLUT4) were obviously down-regulated (p < 0.05) in the longissimus dorsi of the Salmonella infection group." (PMID 35163196, 2022).
salpingitis (1 paper, 2023). Acute or chronic inflammation of the fallopian tube. "In this study, HK2 and MOGAT1 were upregulated and CA4, CNTN3, and ACAN were downregulated in the CN-LPS group, suggesting that LPS-induced salpingitis caused abnormal lipid and sugar metabolism and altered the acid–base balance of the internal environment, degrading the extracellular matrix." (PMID 37978561, 2023).
silicosis (1 paper, 2021). Silicosis is a respiratory disease caused by breathing in (inhaling) silica dust. "We also examined the expression of other key enzymes in the glycolytic pathway and found that the protein and mRNA expression levels of HK2, pyruvate kinase M2 (PKM2), and LDHA were also increased in rats with silicosis." (PMID 34576239, 2021).
small cell lung carcinoma (1 paper, 2022). Small cell lung cancer (SCLC) is a highly aggressive malignant neoplasm, accounting for 10-15% of lung cancer cases, characterized byrapid growth, and early metastasis. "In addition to its role in metabolic regulation, recent study have shown that HK2 can increase stemness of small cell lung cancer cells by increasing ubiquitin-specific protease 11-mediated CD133 stability." (PMID 36335239, 2022).
teratocarcinoma (1 paper, 2019). A germ cell tumor characterized by the presence of an embryonal carcinoma component and a teratoma component. "RNA-Seq analysis of a teratocarcinoma cell line (Tera-1) revealed the extent of HK2 expression from multiple loci and the activity of many of the LTRs in driving expression." (PMID 31333597, 2019). "We also show that in a teratocarcinoma cell line (NCCIT), which has an embryonic stem cell (ESC) phenotype, HK2 expression is high." (PMID 31333597, 2019).
Theileria infection (1 paper, 2014). "This showed that Theileria infection has activated a leukocyte transcriptional programme typical of Warburg glycolysis (e.g. higher expression of hk2 and pkm2), which is normally associated with cells experiencing hypoxia." (PMID 24112286, 2014).
thyroid nodule (1 paper, 2023). A small circumscribed mass in the THYROID GLAND that can be of neoplastic growth or non-neoplastic abnormality. "The current explorative study demonstrated that [18F]FDG uptake in indeterminate thyroid nodules was positively correlated with the expression of GLUT1, GLUT3, HK2, and MCT4." (PMID 36253663, 2023).
thyroiditis (1 paper, 2021). Inflammation of the thyroid gland. "Thyroiditis results in elevation of the mTOR/HIF-1α/HK2/glycolysis pathway in CD4+ T cells." (PMID 34149615, 2021).
tumor (936 papers, 2000 to 2026). "Although mammals express four hexokinase isoforms, overexpression of HK2 is notably linked to aggressive tumor features—including larger tumor size, lymph node metastasis, advanced cancer stages, and elevated alpha‐fetoprotein levels." (PMID 40365984, 2025). "HK1 levels were low in HCLs, whereas HK2, often associated with tumor metabolism, was significantly upregulated in HCLs compared to all primary cells but remained low in HepaFH3." (PMID 40862732, 2025). "HK2, overexpressed in numerous malignancies, has emerged as a prominent therapeutic target because of its association with tumor proliferation, metastatic dissemination, and resistance to radiotherapy and chemotherapy." (PMID 40772466, 2025). "Of note, PGK2 is almost exclusively expressed in germ cells, whereas HK2 overexpression is considered a hallmark of tumor cells." (PMID 41009047, 2025). "We then assessed changes in the target protein HK2, which is associated with glycolytic pathways in tumor cells." (PMID 40998785, 2025). "HIF1 binding to HK2 increases enzyme activity, while loss of HK2 function reduces tumor vascularization." (PMID 40428422, 2025). "A study involving IHC analysis of 157 HCC tumour samples reported that elevated HK2 levels were significantly associated with higher tumour grade and advanced cancer stage." (PMID 41154605, 2025). "B7H3 is also associated with chemotherapy resistance by upregulating HK2 and increasing aerobic glycolysis in tumor cells." (PMID 39335702, 2024). "Research has shown that ZFP36 regulates tumorigenesis by destabilizing the expression of critical genes implicated in both, tumor onset and tumor progression, such as HK2, HIF1α, and c-Myc." (PMID 39026155, 2024). "Conversely, HK2 deficiency by knockdown or knockout of HK2 impaired tumor growth or increased treatment sensitivity." (PMID 39770959, 2024). "Overexpression of HK2 during tumor growth is associated with poor patient prognosis, disease progression, metastasis, and treatment resistance in various malignancies." (PMID 39770959, 2024). "In a mouse xenograft model, the ability of KMP to successfully inhibit tumor growth through loss of hexokinase-2 expression and EGFR activity in cancerous tissues provided further evidence of the anticancer efficacy of the drug." (PMID 38339336, 2024). "Previous studies have reported that HK2 is upregulated in many types of tumors associated with enhanced aerobic glycolysis in tumor cells, including CRC." (PMID 39141107, 2024). "The association with the mitochondria is necessary for HK2-mediated proliferation of hepatocellular carcinoma cells, as disruption of this binding inhibits tumor growth and induces apoptosis." (PMID 38798921, 2024). "Among them, the isoenzyme HK2 is most relevant for energy metabolism in tumor cells, which is closely associated with the initiation and progression of tumorigenesis." (PMID 39330497, 2024). "In LV-HK2 group, high AIMP2 levels led to the retention of increased tumor volume caused by HK2 overexpression compared to the control group." (PMID 37524692, 2023). "3-BP, a halogenated analog of pyruvate, has emerged as a promising anti-tumor agent due to its selective inhibition of critical glycolysis enzymes including HK2, GAPDH, and 3-PGK, thus reducing ATP production and causing cancer cell death." (PMID 37564659, 2023). "High expression of HK2 in tumor and associated mesenchymal stromal cells inhibit glucose uptake in T cells preventing their activation." (PMID 37234972, 2023). "HK2 plays a significant role in the inhibition of mitochondria-mediated apoptosis and has been linked to tumor grade and poor prognosis in GB." (PMID 37298093, 2023). "There are four types of HK isoenzymes, among which HK2 is abnormally highly expressed in the metabolic pathway of tumor cells, and its expression is closely associated with CRC proliferation and metastasis." (PMID 37693915, 2023).
tumor (continued). "Based on its association with the tumor environment, the de novo expression or overexpression of HK2 is associated with poor prognosis, stage progression, metastasis, and/or treatment resistance in a variety of malignancies." (PMID 37190313, 2023). "The HK2 gene (hexokinase 2; MIM#601125) is localized on chromosome 2 at 2p12, encoding HK2, a glycolytic enzyme that boosts tumor glycolysis, progression and metastasis." (PMID 37566048, 2023). "In Hürthle cell carcinoma, HK2 expression was associated with a tumor size larger than 4 cm, MCT4 with extrathyroidal tumor extension, and CA-IX with vascular invasion." (PMID 36253663, 2023). "Induction of HK2 in most tumor cells contributed to their metabolic predisposition to aerobic glycolysis." (PMID 37297015, 2023). "In general, the conversion of glycolysis to OXPHOS, caused by HK-2 inhibition, can be targeted by tumour drugs in two ways." (PMID 37108242, 2023). "Compared with normal cells, HK2 was significantly upregulated in cancer cells and notably associated with tumor cell survival and progression." (PMID 37779163, 2023). "High levels of HK2 are observed in several tumour types and are associated with advanced tumour stage, poor prognosis and metastasis occurrence." (PMID 34754096, 2022). "The ubiquitin ligase HectH9 hijacks Hexokinase 2 (HK2) to mitochondria K63-linked ubiquitination for promoting its dual functions in glycolysis and apoptosis suppression, which in turn contribute to tumor development." (PMID 36202787, 2022). "HexII encodes Hexokinase 2, which is a key mediator of aerobic glycolysis, provides the tumour with a metabolic advantage over its normal tissue of origin." (PMID 35046388, 2022). "In this study, HK2 tumor expression as an indicator of glycolysis was associated with a different immune profile in the TME." (PMID 36320008, 2022). "HK2 catalyzes glycolysis and overexpresses in a variety of tumors; the overexpression of HK2 has been associated with tumor growth and metastasis." (PMID 35265223, 2022). "Current analyses showed that HK2 is positively associated with the infiltration of immune cells in the RCC tumor microenvironment which is a key factor in tumor development." (PMID 35265223, 2022). "High HK2 tumor expression was associated with immunosuppressive/pro-tumorigenic features, especially decreased ratio of CD8 + T-cells to Tregs (rho = −0.415, P = 0.012)." (PMID 36320008, 2022). "HK2 is highly expressed in embryonic tissues and has also been implicated in tumor growth and metastasis with cancer cells generally expressing high levels of HK2 and low levels of HK1." (PMID 35538058, 2022). "Upregulation of HK2, which has a higher affinity to mitochondria, has been associated with enhanced aerobic glycolysis and promotion of tumor growth in many types of cancers, including HBC." (PMID 35712500, 2022). "According to current research, the abnormal expression of HK2 in cancer cells is linked with tumor initiation and malignant growth in many types of cancers." (PMID 35711830, 2022). "The results of the HK2 deficiency study demonstrated that HK2 played an important role in tumor cell proliferation promoted by GCMSCs." (PMID 33718248, 2021). "The protein expression of HK2 was significantly higher in EC tissues compared to normal tissues, and its expression level was associated with a higher tumor grade." (PMID 34174908, 2021). "Overall, this broad range of activities can presumably concur in explaining HK2 remarkable association with a multiplicity of tumor types and with their elevated malignancy, as well as with the resistance to diverse antineoplastic treatments." (PMID 33946854, 2021). "At present, we also found that the expression of HK2 was associated to weight, cancer stages, tumor histology and tumor grade." (PMID 34708035, 2021). "HK2 deficiency also effectively inhibited the promoting effect of GCMSCs on the glucose uptake and lactate production of the tumor cells." (PMID 33718248, 2021).
tumor (continued). "Clinically, overexpression of GLUT1/3 and HK2 was associated with poor clinical outcomes, including more advanced tumor stage, greater tumor burden, higher rate of recurrence and poor survival in HCC patients." (PMID 34359884, 2021). "In recent years, HK2 expression has been reported to be elevated in various cancers, facilitating tumor initiation and maintenance, and has been linked to tumor malignant growth." (PMID 34758823, 2021). "The xenograft mouse model showed that the depletion of HK2 caused a significant delay of in vivo tumor development of CAL27-derived xenograft tumors." (PMID 32424132, 2020). "As a key mediator of aerobic glycolysis, HK2 expression is associated with the promotion of tumor metastasis and growth in many types of cancers." (PMID 33324557, 2020). "Tumour growth reduction was associated with higher expression of miR-125b which correlated with decreasing HK2 expression observed in tumour tissue." (PMID 32843908, 2020). "The HK2 isoenzyme is the form of HK that is most common in tumors, and is associated with tumor initiation and maintenance." (PMID 32273843, 2020). "Next to CA IX, a prognostic role of hexokinase 2 (HK2)—the speed limiting key enzyme of glycolysis—was found with a more than two-fold increased risk of tumor-related death due to a HK2 overexpression in OSCC (Berg T and co-authors, unpublished results)." (PMID 32846951, 2020). "Previous studies have demonstrated that HK2 is required for tumor initiation and maintenance and is linked to tumor metastasis and growth in many types of cancers." (PMID 33324557, 2020). "For instance, HCC tumors express high levels of the hexokinase isoform 2 (HK2), which converts glucose to glucose-6-phosphate, and its expression is associated with the pathological stage of the tumor." (PMID 32542016, 2020). "ROS scavenging by N-acetylcysteine reverted the phenotypes, including diminished number and size of tumor spheres caused by HectH9 or HK2 depletion." (PMID 31201299, 2019). "Through stable isotope tracer approach and functional metabolic analyses, we show that HectH9 deficiency impedes tumor glucose metabolism and growth by HK2 inhibition." (PMID 31201299, 2019). "Overexpression of HK2 is also observed in multiple tumor tissues and is associated with poor prognosis in tumor patients." (PMID 30952834, 2019). "Activation of classical NF-κB is associated with inhibition of the alternate pathway in these tumor types, and in addition promotes HK2 expression, which combined leads to a loss of oxidative metabolism in rhabdomyosarcoma (RMS) and osteosarcoma (OS) cells." (PMID 29696133, 2018). "The elevated rates of glucose metabolism, tumor progression, and the high patient mortality has been predominantly associated with the overexpression of HK2 in different cancers." (PMID 29298880, 2018). "In contrast, HK2 activity inhibited by 3-bromopyruvate (3-BrPA) causes tumor cell death by activating mitochondria-mediated apoptosis signalling." (PMID 29721175, 2018). "Pharmaceutically or genetically intervened inhibition of HK2 results in decreased tumor cell’ aggressiveness while rendering them susceptible to chemo/radio therapy." (PMID 29220380, 2017). "The glycolytic enzyme hexokinase (HK2), which is aberrantly expressed in various types of tumours, is associated with metastasis." (PMID 27926482, 2017). "Searching our published microRNA profile, we find that the tumor-suppressor miR-143, a negative regulator of HK2, is down-regulated in Zn-deficient esophagus." (PMID 29137232, 2017). "According to the pooled results, the abnormal expression of HK2 was significantly associated with some clinical parameters, such as large tumor size, positive lymph node metastasis, advanced clinical stage, and high AFP level." (PMID 28415659, 2017). "Genetic deletion of Hk2 caused a decrease in tumor burden and increased overall survival of Kras-driven lung and ErbB2-driven breast cancer GEMMS." (PMID 28915575, 2017).